KIAA1586 (KIAA1586)
Description:
E3 SUMO-protein ligase; facilitates UBE2I/UBC9-mediated SUMO2 modification of target proteins.
Tractability: PROTAC: UniProt records ubiquitination sites on it; ubiquitination databases record sites on it.
Gene: Protein-coding gene on chromosome 6 (57,046,532 to 57,059,041, forward strand). Ensembl gene ENSG00000168116.
Subcellular location (Human Protein Atlas): Nuclear membrane; Nucleoplasm
Gene Ontology:
Molecular function: SUMO ligase activity
Biological process: protein sumoylation
Genetic constraint (gnomAD): Loss-of-function variants: 4 observed, 6.65 expected, observed/expected ratio (o/e) 0.6, 90% interval 0.29 to 1.36. That is too few expected variants to judge how well the gene tolerates losing a copy. Missense variants: 818 observed, 830.46 expected, observed/expected ratio (o/e) 0.98, 90% interval 0.93 to 1.04. Synonymous variants: 258 observed, 286.35 expected, observed/expected ratio (o/e) 0.9, 90% interval 0.81 to 1.
Homologues: Orthologues: chimpanzee KIAA1586 (95% identical).
Diseases named in the same sentence as KIAA1586 in open-access papers:
KIAA1586 is named in the same sentence as 4 diseases in open-access papers, as found by Europe PMC text mining. Sharing a sentence is not in itself a finding about the gene and the disease. The quoted sentences say what the papers report.
Alzheimer disease (1 paper, 2024). A progressive, neurodegenerative disease characterized by loss of function and death of nerve cells in several areas of the brain leading to loss of cognitive function such as memory and language. "CircRNA KIAA1586 has been identified as a critical risk factor in Alzheimer’s Disease (AD), acting as a competing endogenous RNA (ceRNA) through its binding to AD-associated microRNAs (miRNAs)." (PMID 39507054, 2024).
autism (1 paper, 2017). Persistent deficits in social interaction and communication and interaction as well as a markedly restricted repertoire of activity and interest as well as repetitive patterns of behavior. "Since the expression patterns of both genes are very different, ectopic expression of this gene, not only the haploinsufficiency of KIAA1586, might well be responsible for the presumed association to autism." (PMID 28630856, 2017).
genetic disorders (1 paper, 2025). "Among the prioritized custom CMA genes in the smallest custom CMA NDDi, KIAA1586, ASCL3, BTNL3, SIRPB1, and GLT1D1 exhibit high average shortest path length and low proximity, indicating vulnerability to genetic disorders." (PMID 40869915, 2025).
KIAA1586 also shares sentences with these, for which no sentence is quoted: autism spectrum disorder (1 paper).